CYP24A1 (cytochrome P450 family 24 subfamily A member 1)
Diseases named in the same sentence as CYP24A1 in open-access papers (continued):
Sharing a sentence is not in itself a finding about the gene and the disease.
tumor (continued). "Furthermore, in specimens from vitamin D3-deficient patients, we observed an inverse association between CAF tumoral infiltration and CYP24A1 levels, while CAF infiltration was positively associated with tumor OPN levels (assessed similarly to β-catenin and TGFβ1)." (PMID 38360633, 2024). "Although the information on the influence of SNPs on tumor expression is unclear, it is known that synonymous polymorphisms such as rs6068816, which does not alter the amino acid sequence of CYP24A1, may influence intron splicing." (PMID 36986255, 2023). "Finally, we evaluated whether the anti-tumor efficacy of MDL-811 in CRC is mediated by CYP24A1 downregulation." (PMID 32483423, 2020). "However, in C57BL/6 mice, CYP24A1 kidney expression in the 5000 IU and 100 IU+cal groups (with a similar tendency in 1000 IU+cal) differed between healthy and tumor-bearing C57BL/6 mice—CYP24A1 was downregulated in tumor-bearing and upregulated in healthy mice." (PMID 33172201, 2020). "Therefore, further investigation is needed to examine whether reduced CYP24A1 levels could enhance the anti-tumor efficacy of 1α,25(OH)2D3via suppressing EMT." (PMID 32850381, 2020). "Interestingly, dietary soy increased volume and weight of tumours overexpressing CYP24A1." (PMID 26238339, 2016). "These research findings indicate that CYP24A1 may have tumor promoting effects." (PMID 25544771, 2015). "Considering the negative feedback impact of cyp24a1 on the vitamin D responses, the identification of a novel, translational mechanism of cyp24a1 regulation might open new possibilities to overcome the current limitations of vitamin D as tumor therapeutic option." (PMID 24416388, 2014). "Given that normal mammary cells utilize 25(OH)D3 as substrate for local tissue generation of 1,25(OH)2D3, imbalanced expression of either CYP24A1 or CYP27B1 favoring catabolism could theoretically contribute to escape of developing tumor cells from anti-cancer VDR signaling." (PMID 24982636, 2014). "We selected two genes for this validation experiment – Cyp24A1 from 20q13.2 region, amplification of which was significantly associated with lymph node metastasis and RAB27B from 18q22.2 region deletion of which was significantly associated with tumor grade in combined analyses." (PMID 22363777, 2012). "By carrying tumor-specific biomarkers such as CD63, Cav1, circ-CYP24A1, and miR-1180-3p, exosomes enable highly sensitive and specific detection of early-stage cancers and offer insights into disease progression." (PMID 40303340, 2025). "To investigate the effects of CYP24A1 and TFPI2 on tumor metastasis, we stably transfected BC cells and injected them into nude mice via the tail vein." (PMID 39068476, 2024). "This tumor suppressor miRNA has other targets such as ERBB2, ERBB3 and cytochrome P450 family 24 subfamily A member 1 (CYP24)." (PMID 38954129, 2024). "In tumor-derived endothelial cells, the transcription of one of the VDR target genes, 24-hydroxylase (CYP24A1) is upregulated and this promotes the metabolism of 25-D and 1,25-D." (PMID 38846332, 2024). "The 50 most variable downregulated genes included the cytochrome P450 family 24 subfamily A member 1 (CYP24A1), the onco‐channel TRPV6, and DKK2 (i.e., a Wnt mediator of tumor immune evasion)." (PMID 35079680, 2022). "We found that plasma circ-CYP24A1, circ-ALDH3A2 and circ-DNA2 levels displayed correlations to maximum tumor diameter, tumor thickness, preoperative serum SCC-Ag and serum SCC-Ag 1 month after surgery." (PMID 34109199, 2021). "Dietary soy reduced the tumour volume in GFP bearing xenografts (grey lines with circles), but increased that of CYP24A1 overexpressing xenografts (black lines with circles)." (PMID 26238339, 2016). "Results from mRNA expression analysis show that transcriptional activities of CYP27B1, CYP24A1 and COX-2 are significantly elevated in cancerous lesions compared to mucosal tissue outside of the tumor area." (PMID 24213465, 2012).
tumor (continued). "Data from 105 cancer patients on CYP27B1, VDR, CYP24A1, and COX-2 mRNA expression in relation to tumor grade, anatomical location, gender and age were fit into a multivariate model of exploratory factor analysis." (PMID 24213465, 2012). "During tumor progression elevated CYP27B1 remains constant, whereas COX-2 peaks in low grade and CYP24A1 in high grade cancers." (PMID 24213465, 2012). "In the metastasis group, the top shared upregulated genes were cancer-related with diverse functions, including tumor suppressors (SAMD9 and SEMA3B) and genes involved in growth, survival, cytoskeletal dynamics, motility, invasion, and metastasis (RHOBTB3, CYP24A1 and PTGS2)." (PMID 40605119, 2025). "Tumors in patients with normal plasma 25(OH)D3 levels were also characterized by lower levels of CYP24A1 (assessed in the tumor tissues, not on cancer cells), indicating reduced local degradation of calcitriol." (PMID 38360633, 2024). "As determined by a study conducted on a small cohort of PDAC patients, an overall upregulation of both vitamin D receptors (VDRs) and the vitamin D degrading enzyme 1,25-dihydroxyvitamin-D3 24-hydroxylase (CYP24A1) has been described in tumor regions, with respect to adjacent non-tumorous tissues." (PMID 38732007, 2024). "We observed a significant overexpression of CYP24A1 in this analysis (FC = 7, P = 0.005), even when only matched tumor and adjacent nontumor tissue samples were compared (N = 14, FC = 7.3, P = 0.01)." (PMID 29726119, 2018). "However, it seems that the tumours influenced the renal metabolism of 1,25‐D3 as CYP27B1 expression tended to be lower in the kidneys of mice harbouring CYP24A1‐overexpressing xenografts." (PMID 26238339, 2016). "Regardless of the diet, CYP24A1‐overexpressing xenografts grew faster and were more aggressive, as evidenced by more tumours penetrating the skin." (PMID 26238339, 2016). "These in vitro data support our in vivo data that soy promotes the growth of the tumours overexpressing CYP24A1, regardless of vitamin D levels." (PMID 26238339, 2016). "To test whether CYP24A1 expression was still present in the HT29CYP24A1‐GFP xenografts after 3 weeks in vivo, we analysed mRNA expression in the tumours at the end of the experiment." (PMID 26238339, 2016). "SL exposure also induced changes in the expression of genes involved in metabolic functions in tumor and stem cells (ALDH1B1, ABCB1, SLC3A2, SLC44A2, SLC31A2, SLC7A11, CYP24A1, PTGS2/COX2, PPRC1), cytokines (CCL3L3, GDF15) and growth and differentiation factors (PGF, TGFBR11 and FOXD1)." (PMID 24742967, 2014). "Indeed, previous studies have shown that CYP24A1 inhibition markedly increases the anti-tumor activity of 1,25(OH)2D3 in CRC cells 59, 60, suggesting that inhibition of CYP24A1 transcription by MDL-811 may enhance the efficacy of 1,25(OH)2D3 for CRC treatment." (PMID 32483423, 2020). "As there is evidence for CYP24A1 functional significance in lung carcinogenesis, we investigated whether mRNA levels of this gene are deregulated in 30 tumor tissue samples when compared to 20 adjacent nontumor tissue samples from the NCI‐MD cohort." (PMID 29726119, 2018). "However, in both tumor-bearing and healthy mice, the 25(OH)D3:24,25(OH)2D3 ratio was highly increased in the 100 IU+cal and 1000 IU+cal groups and not changed or slightly decreased in the 5000 IU group, independent of the level of CYP24A1 protein." (PMID 33172201, 2020). "Additional open questions are whether the levels of VDR, CYP27B1 and CYP24A1 and ROR in the tumor cells can also serve as reliable prognostic factors and in what way the level of VDR may affect the efficiency of vitamin D in inhibiting the tumor growth and aggressiveness." (PMID 31235702, 2019). "In our previous study, the less calcemic, CYP24A1 resistant 1,25D(OH)2D3 analog, EB1089, did not reduce VCaP xenograft tumor growth in vivo despite cell growth reduction in vitro and efficacy in LNCaP xenograft tumors." (PMID 28591703, 2017).
cancer (105 papers, 2007 to 2026). A tumor composed of atypical neoplastic, often pleomorphic cells that invade other tissues. "Upregulation of CYP24A1 has been observed in diseases where hypoxia is a key pathogenic component (e.g., cancer)." (PMID 36834800, 2023). "Among these publications reported the associations of CYP24A1 polymorphisms with cancer susceptibility, while the results remain controversial." (PMID 37670334, 2023). "Secondly, this is the first meta-analysis to assess the relationship between CYP24A1 (rs4809957, rs2762939) polymorphism and cancer risk." (PMID 37670334, 2023). "Another side, the studies revealing the methylation of CYP24A1 were included in the analysis due to the methylation was proven to be associated with low expression of CYP24A1 in cancer patients." (PMID 36527000, 2022). "The clinical prognostic value of CYP24A1 remains inconclusive, hence we aim to evaluate the association between CYP24A1 and the drug resistance in cancer patients through a meta-analysis approach." (PMID 36527000, 2022). "The pooled HRs and odds ratios (ORs) with 95% confidence intervals (CIs) were used to explore the association between CYP24A1’s expression or SNP with survival, metastasis, recurrence, and drug resistance in cancer patients." (PMID 36527000, 2022). "Meanwhile, the five studies utilized RT-qPCR to detect the SNP of CYP24A1 which was demonstrated to be associated with cancer risk." (PMID 36527000, 2022). "Five common variants of CYP24A1 were reportedly related to cancer risks, including prostate, breast, colon and pancreatic cancers." (PMID 32762692, 2020). "The associations between CYP24A1 polymorphisms and cancer susceptibility had been evaluated by many studies." (PMID 30813883, 2019). "Second, post-transcriptional regulation by miRNAs is associated with the CYP24A1 overexpression in cancer." (PMID 29657326, 2018). "Changes in promoter methylation and gene amplification have been identified as possible causes of aberrant CYP24A1 expression in cancer." (PMID 23463632, 2013). "CYP24A1, which encodes 1,25-dihydroxyvitamin D 3 24-hydroxylase, has been suggested to play a role in the pathogenesis of many carcinomas." (PMID 24039610, 2013). "Furthermore, studies have shown that increased expression of CYP24A1 was associated with the poor prognosis of patients with different cancer types, including CRC." (PMID 39858498, 2025). "CYP24A1 encodes 24-hydroxylase, a key enzyme that catabolizes 1,25(OH)2D3 into less active metabolites, thereby reducing 1,25(OH)2D3 levels and contributing to cancer development and progression." (PMID 39858498, 2025). "Other than expression level, CYP24A1 gene variants are also correlated with cancer susceptibility." (PMID 40630116, 2025). "Therefore, a comprehensive meta-analysis was performed to better explore the associations of CYP24A1 polymorphisms with cancer risk." (PMID 37670334, 2023). "Therefore, the present meta-analysis aimed to re-evaluate the associations of CYP24A1 polymorphisms with cancer risk." (PMID 37670334, 2023). "Therefore, we performed a comprehensive study to identify the association of CYP24A1 polymorphisms (rs4809960, rs6068816, rs2296241, rs4809957, rs2762939) with cancer susceptibility." (PMID 37670334, 2023). "Similarly, CYP24A1 is aberrantly expressed at high levels and has been implicated as a potential oncogene in colorectal, breast, and other cancers." (PMID 37414755, 2023). "Whether cytochrome P450 24A1 (CYP24A1) polymorphism is associated with cancer susceptibility, the individual study results are still controversial." (PMID 37670334, 2023). "Indeed, overexpression of CYP24A1 has been linked to a poor prognosis in some human cancers, and recently novel small molecule DNA aptamers have been identified that target CYP24A1 with promising anticancer effects." (PMID 37228489, 2023).
cancer (continued). "Afterwards, the HRs (95% CIs) of the populations carrying SNP with certain function in cancer risk were pooled and calculated to be 1.42 (1.16, 1.68), demonstrating that the polymorphisms of CYP24A1 which were correlated to cancer risk were positively associated with poorer prognosis." (PMID 36527000, 2022). "Further, several studies have demonstrated that the increased expression of CYP24A1 may cause resistance to vitamin D anti-cancer actions." (PMID 36362766, 2022). "Additionally, there are also few studies which revealed the polymorphisms of CYP24A1 that were associated with cancer risk and poor prognosis of patients." (PMID 36527000, 2022). "Hence, a meta-analysis of eligible studies was conducted to determine the association of CYP24A1 expression with the prognosis of cancer patients and the resistance to chemotherapy to clarify the exact prognostic value of CYP24A1 in drug resistance prognosis." (PMID 36527000, 2022). "Additionally, CYP24A1 has also been found to be highly expressed in many cancers including ovarian cancer, which is associated with the inverse impact of 25(OH)D3 on cancer risk levels." (PMID 30157901, 2018). "In other cancers, selected SNPs for CYP24A1 may reduce the risk or cancer presentation." (PMID 38927967, 2024). "Although numerous studies revealed that CYP24A1 could act as a therapeutic target in cancers and the SNP of CYP24A1 was associated with increased cancer risk and poor prognosis, it was still unclear whether CYP24A1 expression was significantly related to drug resistance." (PMID 36527000, 2022). "It has been reported that inhibiting CYP24A1 expression enhances the antitumor effect of 1,25(OH)2D3 in various cancer cell types, including CRC cells." (PMID 39858498, 2025). "By inactivating 1,25(OH)2D3, overexpression of CYP24A1 limited biological activities of 1,25(OH)2D3, potentially reducing its effectiveness in inhibiting the proliferation and motility of cancer cells." (PMID 39858498, 2025). "CYP24A1 expression is generally higher in cancer tissues compared to normal tissues, which also correlates with aggressive diseases and poor prognosis." (PMID 40630116, 2025). "Upregulated circRNAs, such as circ-CYP24A1, were principally involved in the immune response, while downregulated circRNAs were modulators in metabolic pathways in cancer cells and RNA transportation." (PMID 38473864, 2024). "The results showed that compared to the normal tissue surrounding cancer, CYP24A1 and TFPI2 were significantly decreased in BC cancer tissue." (PMID 39068476, 2024). "This information was observed in a multiethnic meta-analysis with 761 cases in 4 studies in two types of cancer (lung and colorectal), where increased CYP24A1 protein expression correlated with worse survival (HR = 1.14; 95% CI = 1.02–1.26; I2 = 36)." (PMID 36986255, 2023). "While for genes GREB1, TBX4 and CYP24A1, both HMs showed higher signals in cancer cell lines than that in normal cells." (PMID 37426199, 2023). "Preclinical investigations of autocrine CYP24A1 expression in cancer are similar to systemic regulation of vitamin D metabolism in humans, where upregulation of CYP24A1 prevents pathophysiological effects of hypervitaminosis D." (PMID 36979850, 2023). "Accumulating evidence suggests that high levels of CYP24A1 affect the biological activity of calcitriol in cancer cells." (PMID 35563410, 2022). "In several clinical studies, higher expression of CYP24A1 was shown to be correlated with poor prognosis of various cancer types." (PMID 36527000, 2022). "In our previous study, we had identified CYP24A1 as a potential resistance biomarker for various cancer types." (PMID 36527000, 2022). "Contrarily, the overexpression of CYP24A1 in BrafV600E cancer cells had promoted malignant progression and cancer cell resistance to PLX4720 treatment." (PMID 36527000, 2022).
cancer (continued). "Findings from our meta-analysis demonstrated that CYP24A1’s expression or SNP was correlated with cancer progression and drug resistance." (PMID 36527000, 2022). "As hypoxia can also directly affect calcitriol hydroxylation (due to lack of oxygen) or increase the expression of its inactivating enzymes (CYP24A1;), calcitriol or newly developed analogs can defend against cancer development." (PMID 35406562, 2022). "This systematic study demonstrated that high expression or SNP of CYP24A1 was positively correlated with shorter survival time in various cancer types." (PMID 36527000, 2022). "Apart from this, a substantial number of studies had showed that the CYP24A1 expression had rendered the cancer cells resistance to drugs in xenograft model." (PMID 36527000, 2022). "Higher expression of CYP24A1 in various types of cancer tissues induces local vitamin D insufficiency, thus promoting cancer growth." (PMID 35054977, 2022). "Collectively, the VDR and CYP24A1 were widely expressed in a multitude of bone metastases, pointing to a potential role of vitamin D signalling in cancer progression." (PMID 36362766, 2022). "Collectively, our study indicated that the VDR and CYP24A1 were broadly expressed in bone metastases of breast, prostate, renal, gastro-intestinal, follicular thyroid and other cancers." (PMID 36362766, 2022). "The use of calcitriol and tacalcitol increased the amount of CYP24A1 mRNA in all cancer cell lines used in the study." (PMID 35563410, 2022). "Both pooled ORs and the lower 95% CI values were higher than 1, hence indicating that higher expression of CYP24A1 had indeed promoted the cancer metastasis and recurrence." (PMID 36527000, 2022). "Other researchers have found that SNP rs4809957 located in the three untranslated regions of CYP24A1 gene 20q13.2 interacts with smoking, and 1,25(OH)2D3 plays an antiproliferation role on vitamin D receptor‐mediated human cancer cells." (PMID 34646549, 2021). "It is of interest that an increased activity of CYP24A1 has been observed in different cancers, and CYP24A1 has been identified as a proto-oncogene." (PMID 34064098, 2021). "Secondly, epigenetic modifications, namely DNA methylation of the promoter region leads to modification of CYP24A1 expression in cancer cells." (PMID 34208589, 2021). "It was proposed that increased CYP24A1 expression observed in cancer cells is probably mediated via activation of VDR, because both activity and expression of VDR are downregulated in most types of cancer." (PMID 34208589, 2021). "The overexpression of CYP24A1 has been also documented in numerous other types of cancer, including cervical, ovarian, squamous cell and basal cell carcinoma." (PMID 34208589, 2021). "Fourthly, post-transcriptional regulation via microRNAs is related to the CYP24A1 overexpression in cancer." (PMID 34208589, 2021). "On the other hand, CYP24A1 is overexpressed in cancer and several vitamin D analogues and/or CYP24A1 inhibitors have been tested in preclinical studies." (PMID 32911795, 2020). "CYP24A1, the main enzyme responsible for the degradation of active vitamin D, plays an important role in many cancer related cellular processes." (PMID 30813883, 2019). "Currently, at least four mechanisms responsible for the induction of CYP24A1 in cancer have been proposed." (PMID 29657326, 2018). "As a calcitriol degrading enzyme, CYP24A1 is frequently overexpressed in many cancers; the inhibition of CYP24A1 can increase local concentrations of calcitriol in cancer cells." (PMID 29657326, 2018). "As expected, both SPP1 and CYP24A1 were more induced in CSCs compared to their corresponding bulk cancer cells by the same dose of calcitriol, indicating that CSCs are more sensitive to low dose calcitriol in the activation of the VDR pathway signaling." (PMID 29581858, 2018). "CYP24A1 is a key enzyme in the inactivation of calcitriol, which exerts antiproliferative effects in cancer cells by binding to the vitamin D receptor." (PMID 27834829, 2016).